IL33 (interleukin 33)
Diseases named in the same sentence as IL33 in open-access papers (continued):
Sharing a sentence is not in itself a finding about the gene and the disease.
Alzheimer disease (continued). "IL-33 was found to ameliorate Aβ pathology by reprogramming microglial epigenetic profiles in Alzheimer’s Disease." (PMID 40895552, 2025). "A recent report from our group showed a role for CBD-induced regulation of IL-33 in a murine model of Alzheimer’s disease." (PMID 40177581, 2025). "In animal models of Alzheimer’s disease, IL-33 stimulates microglia and protects against Aβ plaques, despite its association with inflammation." (PMID 39021707, 2024). "The IL-33/ST2 axis has been implicated in many CNS-related diseases and conditions, including Alzheimer’s disease, age-related macular degeneration, multiple sclerosis (MS) and EAE, stroke, CNS injury, and pain." (PMID 37429945, 2023). "The involvement of IL-33 in CNS-related diseases, including Alzheimer’s disease, MS and EAE, highlights its potential as a therapeutic target." (PMID 37429945, 2023). "IL-33 improved Alzheimer's disease-like pathology modulating IL-1β, IL-6, and NLR family pyrin domain containing 3 (NLRP3) genes in the cortices of APP/PS1 mice and decreasing cognitive impairment." (PMID 35224555, 2022). "Recently, it was demonstrated that IL-33 improved Aβ pathology by reprogramming chromatin accessibility and PU.1 transcription factor binding in microglial cells in Alzheimer’s disease." (PMID 36291105, 2022). "IL-33 has been widely reported in Alzheimer's disease (AD), multiple sclerosis (MS), and intracranial infection, but its relationship with ICH is relatively rare." (PMID 33854693, 2021). "Interleukin-33 (IL-33) is a vital IL-1 family member as a cellular alarmin especially after tissue damage, such as spinal cord injuries, stroke, and Alzheimer’s disease (AD)." (PMID 34631212, 2021). "There is data indicating that serum sST2 has significantly higher levels in the early phase of Alzheimer disease patients (with mild cognitive impairment), with a reduced IL-33 expression." (PMID 34821692, 2021). "IL-33 plays a yet poorly understood role in the pathogenesis of Alzheimer’s disease (AD), a condition where deposition of extracellular amyloid beta (Aβ) plaques in the brain and neuronal cell death accompany neuroinflammation." (PMID 32505187, 2020). "IL-33 has been previously involved in cognitive defects observed in neuropathological conditions such as reflected in Alzheimer’s disease, multiple sclerosis, and experimental cerebral malaria." (PMID 32917228, 2020). "The neuroprotective role of interleukin (IL)-33 is supported by numerous preclinical studies, but it remains uninvestigated in clinical studies of Alzheimer’s disease (AD)." (PMID 32678011, 2020). "These further suggest that IL-33 plays a crucial role in the pathogenesis of Alzheimer's disease as a mediator of inflammatory molecules." (PMID 29507527, 2018). "Transcriptomic analysis revealed the decrease in IL-33 expression in the brain of Alzheimer's disease cases and this expression is restricted to the endothelium and vascular smooth muscle cells of cell arteries of both AD and non-AD brains." (PMID 29507527, 2018). "IL-33 expression in the brain was downregulated in Alzheimer's disease (AD) cases compared with controls, and a similar conclusion was drawn by another study." (PMID 29180837, 2017). "Because of its role as promoter of type 2 immune responses and regulator of innate and adaptive immune responses, IL-33 has been explored as therapeutic option in pre-clinical models of Alzheimer’s disease, stroke, cerebral malaria, and transplantation." (PMID 28320438, 2017). "Recent research findings have provided convincing evidence indicating a role for Interleukin-33 (IL-33) signalling pathway in a number of central nervous system (CNS) diseases including multiple sclerosis (MS) and Alzheimer’s disease." (PMID 27455844, 2016). "Other inflammatory biomarkers in Alzheimer’s disease may include IL-33 and the soluble form of its receptor ST2 (sST2)." (PMID 39021707, 2024). "IL-33 is decreased in the brains of patients with Alzheimer’s disease." (PMID 37429945, 2023).
Alzheimer disease (continued). "Moreover, in Alzheimer’s disease, MCs can be involved in releasing IL-33 into amyloid plaques, favoring inflammatory and degenerative processes." (PMID 36362030, 2022). "Several studies reported the involvement of IL-33/ST2 signaling in the pathogenesis of Alzheimer’s disease (AD), multiple sclerosis (MS), experimental autoimmune encephalomyelitis, experimental cerebral malaria (ECM), chronic pain, intracranial hemorrhage (ICH), and stroke." (PMID 36362246, 2022). "The pathogenesis of Alzheimer disease may involve an impaired IL-33/ST2 signaling, with the inhibition of β amyloid phagocytosis and clearance by microglia, which promotes chronic neuroinflammation and amyloid plaque deposition." (PMID 34821692, 2021). "Extending that role into a transgenic mouse model of Alzheimer’s disease, IL33 shifted the activation state of microglia from a proinflammatory profile towards a profile expressing anti-inflammatory genes with improved phagocytosis and again improved fear-conditioned learning." (PMID 34266459, 2021). "Interleukin-33 is a cytokine endowed with pro- and anti-inflammatory properties that plays a still poorly defined role in the pathogenesis of a number of central nervous system (CNS) conditions including Alzheimer’s disease (AD)." (PMID 32505187, 2020). "Conversely, another recent study has suggested that IL‐33 might induce glial cells to release inflammatory molecule and exacerbate neuroinflammation in Alzheimer disease." (PMID 31397082, 2019). "Also, it is reported that IL-33 can modulate microglia in an animal model of Alzheimer‘s disease, but its function in these condition is still unclear." (PMID 29988422, 2018). "Genetic study showed decreased IL-33 expression in the brain of Alzheimer‘s disease patients." (PMID 29988422, 2018). "Furthermore, rodent studies showed that IL-33 had a therapeutic effect in a mouse model of Alzheimer disease, attenuating cellular pathologies and recovering behavioral phenotypes." (PMID 29379874, 2017). "In addition, IL-33 expression is decreased and consistently restricted to vascular capillaries in the brain of Alzheimer’s disease (AD) cases." (PMID 24107076, 2013). "Finally, a transcriptional analysis of brain tissue from patients with Alzheimer's disease revealed that IL-33 expression was decreased compared to control tissues." (PMID 21871091, 2011). "Moreover, this dual function of IL-33 has also been observed in Alzheimer’s disease (AD)." (PMID 32917228, 2020). "Expression levels of IL-33 and its receptor ST2 are strongly increased around the amyloid plaques in the brains of patients with Alzheimer’s disease." (PMID 29379874, 2017). "Our studies have also shown that IL-33 is upregulated in the glia of neurodegenerative diseases such as in Alzheimer’s disease brain, and MPP+ induced IL-33 release from mouse astrocytes in vitro." (PMID 26275153, 2015). "In another study, patients with amnestic mild cognitive impairment or Alzheimer's disease who lacked IL-33 expression showed severe cognitive impairment, whereas patients who presented the IL-33 expression maintained their cognitive performance." (PMID 35224555, 2022). "Therefore, in this review, the critical roles of the IL-33/ST2 pathway in neurological disorders are discussed, particularly in Alzheimer's disease, multiple sclerosis, and experimental cerebral malaria." (PMID 29507527, 2018). "Although IL-33-positive cells (astrocytes and microglia) are significantly increased in Alzheimer’s disease (AD) brains compared to non-AD brains, IL-33 mRNA expression in the brain and circulating IL-33 levels are lower in AD patients than in healthy controls." (PMID 34079543, 2021).
myocardial infarction (51 papers, 2008 to 2026). Gross necrosis of the myocardium, as a result of interruption of the blood supply to the area, as in coronary thrombosis. "A high baseline IL-33 value in patients with their first myocardial infarction was associated with progressive left ventricular volume indices dilatation and left ventricular ejection fraction deterioration." (PMID 36362577, 2022). "Other members of the IL-1 family (such as IL-18 and IL-33) are also implicated in regulation of the inflammatory and reparative response following myocardial infarction." (PMID 26273700, 2015). "Considering an increase in sST2 and a parallel decrease in IL-33 levels during myocardial infarction, one can image the increased risk of patients for coronaries damages." (PMID 24335613, 2013). "IL-33 is highly expressed in both mice and humans following myocardial infarction, and studies utilizing mice that are deficient in ST2 suggest that IL-33 limits tissue destruction that results from myocardial infarction." (PMID 23087690, 2012). "However, some studies associate IL33 with worse cardiac outcomes, particularly post myocardial infarction." (PMID 38472936, 2024). "Another study confirmed that, in the acute phase of myocardial infarction, IL-33 both inhibits the Th1 immune response and promotes heart healing." (PMID 39844544, 2025). "Increasing soluble ST2 levels in the blood of mice after myocardial infarction has brought attention to a putative link between IL33 and cardiovascular disease." (PMID 39844544, 2025). "Among the cytokines, IL-33 is a member of the IL-1 family and has been studied in myocardial infarctions." (PMID 38337827, 2024). "The role of IL-33 in myocardial infarction (MI) was also investigated, where a significant increase in IL-33 levels in patients with MI relative to controls was reported." (PMID 39171751, 2024). "Clinically, serum IL-33 levels are increased in individuals with unstable angina pectoris and acute myocardial infarction compared to stable angina and control groups." (PMID 37509127, 2023). "Experimental data indicate that IL-33 prevents cardiomyocyte apoptosis and improves cardiac function and survival after myocardial infarction through ST2 signaling." (PMID 37371771, 2023). "For example, ANRIL expression levels was increased in heart tissues of acute myocardial infarction mice, and regulated myocardial cell apoptosis through IL-33/ST2 pathway." (PMID 35906216, 2022). "Since IL-1β and IL-33 signaling impacts on wound repair and fibrosis after myocardial infarction, we divided our patient cohort into patients with ICM and DCM." (PMID 34768376, 2021). "In this study, we evaluated the therapeutic efficacy of IL-33-overexpressing bone marrow mesenchymal stem cells (IL33-MSCs) on myocardial infarction (MI) and detected the inflammatory level and cardiac function in rats." (PMID 31547872, 2019). "IL-33 has a protective effect and reduces cardiac hypertrophy and fibrosis after experimental myocardial infarction through ST2 signalling." (PMID 28717200, 2017). "SST2 increased significantly in patients with acute myocardial infarction and both sST2 and IL-33/sST2 ratio correlated with the 6-month prognosis." (PMID 27653273, 2016). "Rather it was the aim of this study to gain additional insights in the pathophysiological role of the ST2/IL-33 system in atherosclerotic disease and myocardial infarction." (PMID 24751794, 2014). "Our study aimed to gain additional insights in a possible pathophysiological role of the ST2/IL-33 system in atherosclerotic disease and myocardial infarction." (PMID 24751794, 2014). "In that respect it is of interest that IL-33 plasma levels varied from 5.4 to 17893.0 pg/mL in patients with myocardial infarction." (PMID 23567618, 2013). "In vitro and in vivo studies demonstrated that IL-33 plays a regulatory role in cardiac dysfunction after myocardial infarction." (PMID 24335613, 2013).
myocardial infarction (continued). "It is known that IL-33 prevents apoptosis, attenuates myocardial infarction and improves cardiac function." (PMID 22853195, 2012). "By restricting caspase-3 function and boosting the generation of the 'inhibitor of cell death' (IAP) group of proteins, IL-33 can potentially diminish the demise of heart muscle cells, lessen heart attack damage and scarring, and improve the pumping ability of the ventricle in a living organism." (PMID 39844544, 2025). "Contrarily, IL33 has shown protective effects in heart failure and myocardial infarction." (PMID 38472936, 2024). "In addition, studies have shown that lncRNA ANRIL triggers myocardial cell apoptosis in acute myocardial infarction through IL‐33/ST2 signal transduction." (PMID 38156382, 2023). "Therefore, we concluded that the IL33-MSC injection reduced the inflammatory level in hearts with myocardial infarction." (PMID 31547872, 2019). "Interleukin 33 is known to have an important influence in the process of myocardial infarction, and the immunoregulatory function of MSCs could be influenced by cell factors." (PMID 31547872, 2019). "In recent years, it has been the subject of much research that IL-33 and ST2 are associated with acute myocardial infarction, acute and chronic heart failure, aortic stenosis, and diastolic dysfunction, and interestingly, increased ST2 levels were generally found to be associated with poor outcomes." (PMID 28614418, 2017). "Therefore, the main diseases affecting serum levels of IL-33 in the previous study may have been myocardial infarction, whereas the main disease affecting serum IL-33 levels in the present study was severe systolic CHF." (PMID 22682001, 2012). "The IL-33/ST2 pathway is a vital mediator of cardiac protection, however it also can exacerbate cardiac remodeling in some situation like post-myocardial infarction." (PMID 40535153, 2025). "This study investigated roles of serum ST2, IL‐33 and BNP in predicting major adverse cardiovascular events (MACEs) in acute myocardial infarction (AMI) after percutaneous coronary intervention (PCI)." (PMID 28623858, 2017). "IL-33 and ST2 were proposed to comprise a cardioprotective signaling system because IL-33 was found to antagonize cardiac hypertrophy as well as hypoxia-induced apoptosis in vitro and in vivo and was thereby shown to protect mice from experimental pressure overload and myocardial infarction." (PMID 24751794, 2014). "In vitro and animal model studies have demonstrated that IL33/IL1RL1 isoform A signaling protects cardiomyocytes from apoptosis by suppressing Caspase 3 activity and promoting the expression of anti-apoptotic proteins in vitro and improves survival in experimental myocardial infarction (MI) animals." (PMID 21629437, 2010).
diabetes (48 papers, 2011 to 2026). "Research on the IL-33/sST2 axis in pregnancies complicated by diabetes indicates that these biomarkers are associated with maternal metabolic disorders and inflammation." (PMID 41975695, 2026). "IL-33 has emerged as a pleiotropic cytokine with both protective and pathogenic roles in diabetes, depending on the disease type, tissue microenvironment, and stage of disease progression." (PMID 40804870, 2025). "Taken together, our results suggest that deficiency of IL-33 leads to sustained inflammation, enhanced inflammatory cytokine expression and gliosis in the retina during diabetes." (PMID 37671525, 2023). "Mansell’s study also found the elevated IL-33 level is associated with age, diabetes, serum phosphorus, microalbuminurea, and diminished GFR, which suggests that IL-33 increases the cardiovascular burden in renal transplant recipients." (PMID 28387719, 2017). "Exogenous factors (such as drug toxicity, toxins, contrast agents, and chemotherapy), kidney transplantation, and diseases associated with nephropathies (SLE, renal ischemia, and diabetes) lead to upregulation of IL-33 in renal tissue." (PMID 28387719, 2017). "Thirdly, high IL-33 levels were associated with diabetes (p = 0.030) and high serum phosphate levels (0 = 0.045), which are both associated with vascular diseases." (PMID 26544186, 2015). "The increased glial activation could be the consequence of exaggerated diabetes-induced neuronal damage, in addition to IL-33 deficiency-mediated dysregulated retinal immune regulation." (PMID 37671525, 2023). "In such patients, higher circulating IL-33 is associated with diminished glomerular filtration rate, age, diabetes, serum phosphorus and microalbuminuria, as well as with higher score for major adverse cardiovascular events, supporting a role for IL-33 in the cardiovascular burden for KDR." (PMID 30769901, 2019). "Preliminary data mostly from animal models suggest the sST2/IL-33 pathway may have causal relevance for vascular disease and diabetes and thus point to a potential novel inflammatory link to cardiometabolic disease." (PMID 23112853, 2012). "Among the biomarkers elucidating the relationship between diabetes and inflammation, the interleukin-33 (IL-33)/ST2 signaling pathway is of particular interest." (PMID 41975695, 2026). "A recent study reported that YAP inactivation coincides with reduced IL-33 expression levels, with intranuclear YAP directly regulating IL-33 expression in human periodontal ligament fibroblasts in an in vivo model of diabetes-associated periodontitis." (PMID 41374934, 2025). "CA has been shown to improve renal glomerulosclerosis and interstitial fibrosis in diabetes by modulating oxidative stress via IL-33/ST2 signaling." (PMID 39519465, 2024). "The deletion of IL-33 enhanced diabetes-induced retinal inflammation, evidenced by upregulated pro-inflammatory cytokine expression (Ccl2, Il1b, Il6, Tnf, Tgfb and Inos), sustained gliosis and microglia activation." (PMID 37671525, 2023). "The amplitudes of both a- and b-waves in 9-month-old Il33−/− diabetic mice (6 months of diabetes) were further reduced compared with those in WT counterparts." (PMID 37671525, 2023). "The upregulation of IL-33 in Müller cells during diabetes is a countermeasure seeking to support damaged neurons and restore impaired retinal NVU by regulating glutamate metabolism, neurotransmitter recycling and the secretion of neurotrophins." (PMID 37671525, 2023). "The deletion of IL-33 further exacerbated the diabetes-induced retinal and photoreceptor layer thinning at 3 months and 6 months of diabetes, compared with that in WT counterparts." (PMID 37671525, 2023). "The deletion of endogenous IL-33 accelerated neuroinflammatory, gliotic and degenerative pathology during diabetes." (PMID 37671525, 2023). "Subsequently, the increased expression of Il33 in the diabetic retina was confirmed by RT-qPCR after 6 months of diabetes." (PMID 37671525, 2023).